AGO2 (argonaute RISC catalytic component 2)
Diseases named in the same sentence as AGO2 in open-access papers (continued):
Sharing a sentence is not in itself a finding about the gene and the disease.
cancer (continued). "To understand the underlying mechanism of different Ago2/CAV1 interactions in cancer cells and normal epithelial cells, we investigated the regulation of Ago2/CAV1 interaction through the charged residues of Ago2." (PMID 38649663, 2024). "Taken together, our results indicate that an intact nuclear lamina is required to maintain cytoplasmic localization of AGO2 in certain cancer cells." (PMID 38994560, 2024). "To analyze the association of Ago2 with endosomes, we observed that the levels of Ago2 overlapping with endosome marker EEA1 in A549 cancer cells were higher than that in BEAS-2B normal lung epithelial cells (Figs. 2Diii and EV2E)." (PMID 38649663, 2024). "Blocking Ago2/CAV1 interaction in cancer cells decreased lung targeting of circulating cancer cells." (PMID 38649663, 2024). "Blockage of Ago2/CAV1 interaction in A549 cancer cells with P2 peptides also made the cells sensitive to anoikis, which is a hallmark of EMT." (PMID 38649663, 2024). "Since EMT in cancer cells contributes to drug resistance, stemness, and invasiveness of cancer cells, we examined the effects of Ago2/CAV1 interaction on these cancer cell properties." (PMID 38649663, 2024). "Corresponding with the increased CAV1 distribution in the plasma membrane fractions, increased Ago2 proteins were detected in the plasma membrane fractions of cancer cells (PM)." (PMID 38649663, 2024). "To determine the role of Ago2/CAV1 interaction in Ago2 function, we used miRNA arrays to examine the levels of miRNA in cancer cells in which Ago2/CAV1 interaction was inhibited by P2 or P2S peptides." (PMID 38649663, 2024). "We uncovered that the downregulation of Lamin A in cancer cells, an alteration promoting cancer aggressiveness, is sufficient to trigger AGO2 nuclear influx accompanied by profound impairment of RNAi in both the cytoplasm and nucleus of Lamin A KO cells." (PMID 38994560, 2024). "Blocking Ago2/CAV1 interaction in cancer cells with P2 peptides decreased the numbers of tumorsphere-forming cells in the A549 cancer cell populations and HCC1806 cancer cell populations (Fig. 4Dii)." (PMID 38649663, 2024). "In this study, we compared Ago2 distribution among the plasma membranes, endosomes, and ER of normal epithelial cells and cancer cells." (PMID 38649663, 2024). "To probe AGO2 nuclear localization in cancer cells, we performed biochemical fractionation experiments in twelve different human cell lines and detected fluctuating levels of AGO2 between the cytoplasmic and nuclear fractions." (PMID 38994560, 2024). "The association of Ago2 and CAV1 on the plasma membranes increases in cancer cells (i.e., HCC1806, MDA-MB-231, and A549 cells), compared to that of normal epithelial cells." (PMID 38649663, 2024). "Suppression of SIRT2-mediated deacetylation reduced the invasion and tumorsphere formation of cancer cells, and K212R substitution in Ago2 prevented TM from exerting the same effect." (PMID 38649663, 2024). "We identified in the current study a unique interaction between Ago2 and CAV1, which can be regulated through lysine 212 acetylation in the CBM of Ago2, in cancer cells." (PMID 38649663, 2024). "The distribution of Ago2 on the plasma membranes of normal epithelial cells and cancer cells was further examined with immunofluorescence analysis." (PMID 38649663, 2024). "In contrast to P2S peptides, P2 peptides decreased Ago2 proteins in the membrane fraction (MF) of cancer cells (Aii)." (PMID 38649663, 2024). "Blocking Ago2/CAV1 interaction in cancer cells with P2 peptides decreased the migration and invasion of A549 cancer cells and HCC1806 cancer cells (Fig. 4Eii) in Boyden chambers." (PMID 38649663, 2024). "In this study, we found a relationship between Lamin A levels and AGO2 subcellular localization in cancer cells." (PMID 38994560, 2024). "Compared to 31 other cancers in the TCGA dataset, the degree and significance of the prognostic impact of AGO2 expression are unique to ACC." (PMID 39404265, 2024).
cancer (continued). "Disruption of Ago2/CAV1 interaction by P2 peptides resulted in fluctuations in different miRNAs in cancer cells." (PMID 38649663, 2024). "The levels of Ago2 overlapping with CAV1 in A549 cancer cells (arrowheads) were higher than that of BEAS-2B normal lung epithelial cells (Di)." (PMID 38649663, 2024). "In this condition, the sum of our findings indicates that a portion of AGO2 redistributes to the nucleus, where it interacts with RNA processing factors, possibly facilitating the cancer phenotype." (PMID 38994560, 2024). "In this study, we observed that CBM of Ago2 is necessary for Ago2 to be sorted into the EVs of cancer cells." (PMID 38649663, 2024). "We analyzed the mRNA expression levels of miRNA machinery components (DROSHA, DGCR8, XPO5, RAN, DICER, TARBP2, and AGO2) utilizing mRNA-Seq data from The Cancer Genome Atlas (TCGA) and The Genotype-Tissue Expression (GTEx) projects." (PMID 39404265, 2024). "The results indicated that blockage of Ago2/CAV1 interaction in A549 cancer cells with P2 peptides decreased cell viability under paclitaxel (Pac) and gefitinib (Gef) treatment, thereby attenuating drug resistance." (PMID 38649663, 2024). "The association of Ago2 and CAV1 on plasma membranes was decreased by blocking Ago2/CAV1 interaction with P2 peptides in cancer cells (i.e., HCC1806 and A549 cells)." (PMID 38649663, 2024). "This condition-dependent interaction suggests a regulatory role of Ago2/CAV1 interaction in the distribution and function of Ago2 in carcinoma progression and metastasis." (PMID 38649663, 2024). "In fact, high levels of AGO1-4 in non-cellular/non-vesicular fractions have also been reported in other cancer studies and AGO2 secretion in ENPs is proposed to be a common feature of cancer cells." (PMID 37397375, 2023). "The ubiquitinated AGO2 restrains miRNA-mediated gene silencing, thereby facilitating global mRNA accumulation in cancer cells." (PMID 38017534, 2023). "Previously, the ability of MSI1 to shuttle into cytosol was revealed, where it functioned to manipulate mRNA stability via its cytosolic binding partner AGO2 thereby promoting cancer progression." (PMID 35158774, 2022). "Several lines of evidences indicated intragenic LINE-1 hypomethylation influence their host genes in cancer and many other aspects of genomic biology in an Argonaute 2 (AGO2)-dependent manner." (PMID 35685648, 2022). "It is worth noting that in the same paper, the authors reported that BAG3 knockdown in cancer cells favors the recruitment of Argonaute 2 (Ago2) to IL‐6 mRNA, which results in the IL‐6 mRNA destabilization and finally in the reduction of fibrosis onset." (PMID 34741483, 2022). "Mechanically, the AGO2-mediated RISC complex promotes cancer cell outgrowth, survival, and motility by suppressing the tumor suppressor PTEN (phosphatase and tensin homologue on chromosome 10) and activates phosphatidylinositol-3-kinase (PI3K)/AKT signaling." (PMID 36613808, 2022). "Using several cellular models of mutant HRAS and NRAS-driven cancers, this study evaluated the interaction of AGO2 with these RAS isoforms and elucidated the functional implications of this interaction." (PMID 35923912, 2022). "Hypoxic conditions within cancer cells stimulate EGFR to phosphorylate AGO2 at Tyr393, resulting in decreased AGO2 function that causes decreased DICER–AGO2 interaction, leading to decreased miRNA maturation and function." (PMID 35885514, 2022). "The dysregulated expression of the genes encoding AGO proteins, with emphasis on AGO2 and, to a lesser extent AGO1, was demonstrated in neoplastic tissues of numerous cancer types." (PMID 33668654, 2021). "In contrast, circ0005276 and circ-AGO2 are highly expressed in PCa and play a role in promoting cancer cell proliferation and migration." (PMID 34696782, 2021).
cancer (continued). "Despite the large body of data documenting upregulation of the AGOs in numerous types of cancer, melanoma tumors are characterized by lower expression of AGO2 compared to other neoplastic transformations, or even normal tissues." (PMID 33668654, 2021). "This interaction suppresses HOTAIR expression in an Ago2 (Argonaute2)-dependent manner, and reduces the proliferation and invasion ability of cancer cells." (PMID 33540611, 2021). "Here the authors show that inactivation of proteins involved in microRNA-mediated gene silencing, such as ANKRD52 or AGO2, confers resistance to T cell-mediated immune response in a preclinical cancer model." (PMID 34853298, 2021). "For instance, circAGO2, a circRNA generated from AGO2 gene, directly interacts with HuR, which activates HuR to mediate AGO2/miRNA dependent gene silencing to drive cancer progression." (PMID 33539420, 2021). "Given the impact of the presented advances in the delineation of AGO1 and AGO2 dysregulation and activity in cancers of various origin, the broad function of the AGOs in neoplastic transformation will be further documented in the foreseeable future." (PMID 33668654, 2021). "In our study, we identify the MSI1/AGO2 interaction by proteomic analysis from immunoprecipitation in cancer cells." (PMID 31903115, 2020). "As a key regulator of miRNA function and maturation, AGO2 has been found to be overexpressed in various types of human cancers, including breast, gastric, and head and neck cancers." (PMID 32138313, 2020). "In HCC, SNHG11 regulated proliferation, migration, apoptosis, and autophagy of cancer cells through a hsa‐miR‐184/AGO2 axis." (PMID 33232580, 2020). "Here, inspired by the stability of naturally occurring AGO protein/miRNA complexes in the blood circulation, we have designed AGO2 conjugated SPIONs as tumor targeted miRNA delivery vehicles for gene therapy of cancer." (PMID 32345308, 2020). "Despite identified functions of AGO2 in different types of cancer being contradicted, its dysregulation has been implicated in recent years in tumorigenesis." (PMID 32138313, 2020). "With biochemical, cellular and clinical approaches, we have systemically demonstrated that acetylation of AGO2 was essential for pre-miR-19b1 processing into mature miR-19b, which are proven to promote cancer progression." (PMID 30305728, 2019). "These exosomes, when isolated from the blood of cancer patients, can alter the target cell transcriptome in a canonical Dicer-AGo2-dependent miRNA-mediated gene silencing, and promote oncogenic transformation of normal epithelial cells." (PMID 31877735, 2019). "This binding subsequently prevents AGO2 from forming the AGO2-miRNA complex and inhibits gene silencing, which ultimately drives cancer progression." (PMID 30774645, 2019). "In this study, we identify a novel PTM of AGO2, acetylation, and demonstrate that acetylation of AGO2 promotes cancer progression by specifically increasing miR-19b biogenesis." (PMID 30305728, 2019). "The miRNA biogenesis factors Dicer and Ago2 are degraded by autophagy through recognition of the autophagy receptor to promote cancer progression." (PMID 30657254, 2019). "Loss of miR-100-5p was concurrently reported to promote PCa metastasis through regulation of migration, invasion, EMT, and stemness of cancer cells by up-regulating AGO2 expression." (PMID 28642484, 2017). "Combined with the relationships between AGO2 and tumorigenesis and cancer progression, the results reported here open new avenues for understanding the actions, and resulting effects, of ERβ and AGO2 in cancer cells." (PMID 29017520, 2017). "Alternatively, there is evidence that the stability of AGO2 in the RISC is enhanced by EGFR/ERBB1 through MAPK signaling in cancer cell line MDA-MB-231." (PMID 27701455, 2016).
cancer (continued). "Previous studies have shown that several types of cancer are associated with alterations to miRNA machinery genes, such as DROSHA, DICER1, XPO5, and AGO2." (PMID 26147304, 2015). "Argonaute 2 (AGO2), a central component of RNA-induced silencing complex, plays critical roles in cancer." (PMID 26545861, 2015). "Further studies indicated that the AGO2 is involved in several steps of cancer development, including cell proliferation, differentiation, apoptosis, migration and invasion." (PMID 26545861, 2015). "Overexpression of AGO2 has been shown to inhibit cancer cell proliferation and migration in mice models." (PMID 24904827, 2014). "The expression levels of Drosha, DGCR8, Dicer, XPO5, AGO2, and TRBP have all been associated with several cancers." (PMID 24904827, 2014). "In the present study, we investigate the nuclear functions of Ago1 and Ago2 – the major facilitators of miRNA activity – from a global prospective using human cancer cells as a model system." (PMID 24086155, 2013). "In conclusion, intragenic L1 produces L1 RNA upon hypomethylation in cancer tissues,and the host gene is consequently down-regulated when AGO2 is present." (PMID 21423624, 2011). "Finally, we compared our list with the biochemically-proven miR-1 targets identified in an Argonaute-2 (Ago2) recruitment study on ECs42, to arrive at the final list of 24 genes with the highest likelihood of being targeted by miR-1 in the cancer field." (PMID 40155749, 2025). "It supports that Ago2/CAV1 interaction is not predominantly responsible for Ago2 association with endosomes in cancer cells." (PMID 38649663, 2024). "To understand the underlying mechanism of Ago2/CAV1 interaction differently mediated by Ago2 lysine 212 in cancer cells and normal epithelial cells, we investigated the regulation of Ago2/CAV1 interaction through modification on Ago2 lysine 212, which interferes with the positive charge of lysine." (PMID 38649663, 2024). "We observed that S387 phosphorylation of Ago2, the determinant of Ago2 association with endosomes in cancer cells, did not affect Ago2/CAV1 interaction (Fig. EV1H)." (PMID 38649663, 2024). "Therefore, further research is required on the effects of Ago2/CAV1 interaction on cancer therapy and the methods of selectively targeting Ago2/CAV1 interaction in clinical cancer therapy." (PMID 38649663, 2024). "In this study, we discovered that Ago2 is secreted by cancer cells through EVs." (PMID 38649663, 2024). "Furthermore, disrupting Ago2/CAV1 interaction also decreased the level of miRNA-3613-3p in the cancer cell-derived EVs." (PMID 38649663, 2024). "Since the positive charge of Ago2 K212 is essential for Ago2/CAV1 interaction and acetylation of Ago2 K212 neutralizes the positive charge, we further explored the deacetylases that may attenuate Ago2 K212 acetylation in cancer cells for Ago2/CAV1 interaction." (PMID 38649663, 2024). "The elevated miRNA-3613-3p in cancer cells with Ago2/CAV1 interaction can be released via EVs." (PMID 38649663, 2024). "In addition, blockage of Ago2/CAV1 interaction in A549 cancer cells with P2 peptides increased the cells’ resistance to disassociation through 0.05% trypsin treatment, which is an epithelial phenotype." (PMID 38649663, 2024). "We examined whether Ago2/CAV1 interaction is required for cancer cell dissemination from primary tumors." (PMID 38649663, 2024). "Because deacetylated Ago2 K212 is responsible for Ago2/CAV1 interaction and the interaction-mediated miRNA function in cancer cells, we evaluated the effects of Ago2 K212 acetylation on the Ago2/CAV1 interaction-dependent behaviors of cancer cells (i.e., invasion and tumorsphere formation)." (PMID 38649663, 2024). "In A549Ago2-KO/HA-AID-Ago2Wt/HA-Ago2∆ cells treated with IAA, which only expressed HA-Ago2∆, CAV1 was not precipitated with HA-Ago2∆ by anti-HA antibodies, indicating that Ago2/CAV1 interaction was blocked in IAA-treated cancer cells with an auxin-inducible degron system (Fig. EV3Ci,Cii)." (PMID 38649663, 2024).
cancer (continued). "Among 32 cancer types in TCGA, the prognostic significance of AGO2 was most prominent in ACC." (PMID 39404265, 2024). "We further evaluated whether the elevated miRNAs in cancer cells in which Ago2/CAV1 interaction is maintained could be released via EVs into the circulatory system and be detected in plasma as biomarkers." (PMID 38649663, 2024). "Therefore, loss of Lamin A triggers nuclear AGO2 translocation, FAM120A mediated RNAi impairment, and upregulation of oncogenic miRNAs, facilitating cancer cell proliferation." (PMID 38994560, 2024). "Similarly, miR-100 has a negative impact on prostate cancer cells by down-regulating the oncogene argonaute 2 (AGO2), which can mediate stemness factors of cancer cells such as OCT4, Krüppel-like factor 4 (KLF4), and c-myc." (PMID 36969009, 2023). "Next, we sought to determine whether there are differences in overall survival between TP63 and Ago2 expression in human cancers." (PMID 35459267, 2022). "As previously reported, AGO2 overexpression is crucial to turn on the transcription of numerous oncogenic proteins and RNA transcripts to promote pluripotent cell development and reprogram the tumorigenic potential of several types of cancer." (PMID 36613808, 2022). "Duplexes formed by these 1-nt-shorter miRNA isoforms were proved to be inefficiently loaded into AGO2 protein hampering the formation of functional RISCs, which might be related to the reduction of miRNA dosage in cancer cells." (PMID 39872754, 2022). "Our present data revealed for the first time that peptidic disruption to the MSI1/AGO2 complex known for promoting cancer stemness and progression could lead to encouraging therapeutic efficacy at both in vitro and in vivo levels." (PMID 35158774, 2022). "Furthermore, hsa-miR-99a which targeting AGO2 was only down-expressed in 8 cancers, while hsa-miR-93 which targeting CYFIP1 was only upregulated in 12 cancers." (PMID 36339001, 2022). "Argonaute-2 (AGO2) overexpression was reported to be associated with microRNA (miRNA) biogenesis, supporting the self-renewal and differentiation characteristics of cancer stem cells (CSCs)." (PMID 36613808, 2022). "Additionally, core miRNA processors and related factors, such as Drosha, Dicer, TRBP, and Ago2 are important in cancer progression." (PMID 36139366, 2022). "And the expression of AGO2 was significantly higher in cancer tissues than in stromal tissues." (PMID 33846300, 2021). "Often up-regulated in cancer, AGO2 is involved in chromatin remodeling and alternative splicing." (PMID 33859327, 2021). "Ago2 and let-7 miRNAs levels are frequently dysregulated in cancers." (PMID 33599613, 2021). "Thus, our studies reveal that M1-Ubi of AGO2 is an essential mechanism modulating mRNA turnover in the miRNA pathway in hypoxic cancer cells." (PMID 34518544, 2021). "We found that AGO2 was significantly expressed at lower levels in cancer tissues." (PMID 33846300, 2021). "Overall, circAGO2 might regulate cancer progression by facilitating the human antigen R (HuR)-inhibited effects of argonaute 2 (AGO2)-miRNA complexes." (PMID 32213977, 2020). "Target selection for miR-100 was more challenging as there are far less validated targets and even less related to cancer progression, thus we analyzed the validated survival related target mammalian target of rapamycin (mTOR), as well as Ago1 and Ago2 which are predicted targets of miR-100." (PMID 32872485, 2020). "circ-AGO2 promotes the growth, invasion, and metastasis of cancer cells in vitro and in vivo." (PMID 32140311, 2020). "Indeed, it has been found that the Argonaute-2 (AGO2) protein targets intronic LINE-1 pre-mRNA complexes leading to down-regulation of gene expression in cancer cells." (PMID 31293617, 2019). "Together, these results indicate that Ago2 could play a role in cancer progression or response to treatments." (PMID 31324173, 2019).